VIM (vimentin)
Diseases named in the same sentence as VIM in open-access papers (continued):
Sharing a sentence is not in itself a finding about the gene and the disease.
colon carcinoma (continued). "Our experimental results are consistent with the results obtained in some previous studies, indicating that P2 × 7 receptor can regulate the expression of MMP-2, E-cadherin, N-cadherin, Vimentin, Zeb1, and Snail, and affect the invasion and migration of colon cancer cells." (PMID 33330466, 2020). "Inhibition of SUMO1P3 repressed proliferation, migration, invasion and pro-angiogenesis of colon cancer cells in vitro, and reduced growth, liver metastasis and vascularization of colon cancer in vivo by decreasing cyclin D1, vimentin and VEGFA but increasing E-cadherin expression." (PMID 32185172, 2020). "Thus, we propose that modulation of the TUBB4B protein is critical for vimentin-microtubules interaction in invasive colon cancer cells." (PMID 31375012, 2019). "After miR-205-5p transfection (10 nM) experimental cells and associated controls were stained with antibodies directed towards E-cadherin and Vimentin in order to assess the relative expression, disposition, and preponderance of the two molecules within the colon cancer cells." (PMID 29352232, 2018). "In addition, the western blot results demonstrated that Vimentin expression was upregulated and E-cadherin was downregulated in LPS-treated colon cancer cells." (PMID 29308184, 2018). "Collectively, these results indicate that the combination between the two antagonist genes (CDH1 and VIM) could represent a valuable prognostic marker in colon cancer." (PMID 29352232, 2018). "Knockdown of Snail suppressed the expression of vimentin induced by ethanol in colon cancer cells." (PMID 28538665, 2017). "Different isoforms of vimentin have also been reported in a variety of tissues and tumor types, including six isoforms in pancreatic tumor cell lines, four isoforms in lung tumor cell lines, nine in colon tumor cell lines and 33 in ovarian tumor cell lines." (PMID 28670517, 2017). "Furthermore, the association between the migration of colon cancer cells and the levels of TM and epithelial-to-mesenchymal transition (EMT) markers (fibronectin, vimentin and ezrin) was confirmed in HT29 and DLD-1 cells." (PMID 27512995, 2016). "In this study, TM suppression in colon cancer cells enhanced fibronectin, vimentin, and ezrin expression levels, which could increase the migratory capacity of colon cancer cells." (PMID 27512995, 2016). "In this study we chose to use a gene, vimentin, in which increases in methylation have demonstrated a strong correlation with the development of colon cancer, and that has been used as the target for a commercialized fecal DNA methylation diagnostic test (ColoSure, LabCorp)." (PMID 27542211, 2016). "We demonstrated here that DDA1 overexpression promotes the EMT of colon cancer cells with changes in cell morphology, along with downregulation of the epithelial protein E-cadherin and upregulation of the mesenchyme molecules N-cadherin and Vimentin." (PMID 26942699, 2016). "CPMV were previously shown to bind to surface vimentin on cells and these nanoparticles were capable of localizing to HT-29 tumors (a highly aggressive human colon carcinoma line) in vivo using the chick chorioallantoic membrane experimental human tumor xenograft tumor model." (PMID 24212937, 2011). "Interestingly as seen from the figure, not all cells had detectable surface vimentin expression; this is consistent with what was found for surface vimentin expression on cervical, breast and colon cancer cell lines." (PMID 24212937, 2011). "The aim of this study, was to investigate whether vimentin expression in colon cancer tissue is of clinical relevance." (PMID 17325702, 2007). "To investigate whether the effects of fruquintinib on the migration and invasion of colon cancer cells are associated with EMT, we detected the expression of N-cadherin, E-cadherin, MMP-9 and vimentin following treatment with different concentrations of fruquintinib." (PMID 40134588, 2025).
colon carcinoma (continued). "One study showed that inducing the expression of pri-miR-34a using doxycycline could result in the down-regulation of vimentin and the upregulation of E-cadherin in human colon cancer cell SW480, suggesting that miR-34a can negatively regulate EMT to inhibit proliferation and invasion." (PMID 30781524, 2019). "Similarly, BRG1 loss was also statistically correlated with increased expression of Vimentin (~4-fold; two-tailed t-test, p = 8.4E-04), and the largest changes were observed in liver and colon tumors (10-fold and 6-fold, respectively; p = 4E-03 and p = 2E-02, respectively)." (PMID 27486753, 2016). "In colon cancer cells, ADAMTS6 knockdown increased E-cadherin expression and decreased N-cadherin and vimentin, while ADAMTS6 overexpression had an opposite effect." (PMID 41465277, 2025). "Patient colon tumor tissue immunostaining revealed that areas of CXCL5 expression occur within the CAF-rich stromal compartment, as shown by colocalization with vimentin." (PMID 41392310, 2025). "Studies in lung and colon cancer have shown that novel HDAC inhibitors increase E‐cadherin expression, while decreasing vimentin and Slug expression." (PMID 40344465, 2025). "In the population of cells isolated from distal colon tumors, the relative and absolute numbers of CD3+CD8+ lymphocytes and vimentin+ cells in the SH mice were statistically significantly higher than in the TH mice." (PMID 39063041, 2024). "Immunofluorescence staining validated the characteristics of both organoids and fibroblasts, showing high expression of epithelial cell markers (EPCAM), colon cancer markers (CK20), proliferation markers (KI67), and fibroblast markers (VIM, SMA)." (PMID 38921017, 2024). "In line with this, Slug and Vimentin was also downregulated in tumors in situ of SYT1 overexpression group mice, suggesting that SYT1 suppressed the colon cancer cells metastasis." (PMID 37958455, 2023). "In colon cancer, the knockdown of FXR increased the migration of colon cancer cells by inducing the protein expression of EMT markers such as vimentin, snail, slug, fibronectin, and FAK." (PMID 35563650, 2022). "VIM and CDH1 appear to be ARID1A's molecular targets in colon cancer, which improve colon cancer cell viability, invasion and proliferation, especially in cells with ARID1A downregulation." (PMID 36420658, 2022). "Mechanism studies have reported that SPHK1 increases the expression of Slug, vimentin, N-cadherin, and FAK in colon cancer Notably, the active interaction of SPHK1 or S1P with ERK pathway promotes autophagy in colon cancer." (PMID 35965565, 2022). "Coexpression correlation analysis results showed that in colon cancer tissues, the coexpression of LIMK1 was positively correlated with EMT marker Vimentin." (PMID 35265128, 2022). "In colon cancer, lncRNA H19 competitively combined with miR-138 and miR-200a, up-regulating the expression of key genes in EMT (VIM, ZEB1, and ZEB2), and promoting the progress of EMT." (PMID 35094653, 2022). "DCLK1 contributes to the promotion of EMT by means of the overexpression of mesenchymal markers (Vimentin) and transcriptional regulators (ZEB1) and the downregulation of the epithelial marker E-cadherin in colon cancer cells." (PMID 35717205, 2022). "Since the expression of MnSOD is associated with the regulation of EMT, the expression of mesenchymal markers (fibronectin, vimentin, and N-cadherin), epithelial markers (occludin and E-cadherin), and MMP-9 was examined in three colon cancer cell lines." (PMID 35883447, 2022). "In conclusion, CRC cells with ARID1A silencing had higher levels of VIM and lower levels of CDH1 expression, which are both positively correlated with ARID1A in colon cancer tissues." (PMID 36420658, 2022). "Corroborating the role of HO-1 as oncoprotein, in colon cancer cells the glucose-regulated protein 78 (GRP78) enhances migration and invasiveness by inducing vimentin expression, in turn reducing E-cadherin level, and triggering Nrf2/HO-1 signaling." (PMID 36290720, 2022).
colon carcinoma (continued). "Co-culture with Schwann cells increased the expression of mesenchymal markers, such as ZEB1, Vimentin, and N-cadherin, and attenuated the expression of epithelial markers, such as E-cadherin and ZO1 in colon cancer cells." (PMID 36522730, 2022). "PTK6 knockdown resulted in a decrease in E-cadherin and ZO-1 epithelial markers and an increase in vimentin, ZEB1, and claudin-1 mesenchymal markers via STAT3-MEK5/ERK5 in colon cancer cells, which was reversed by PTK6 reintroduction." (PMID 33572742, 2021). "Consistently, the combined treatment of Aspirin and Cisplatin obviously attenuated the expression of main EMT-related proteins N-cadherin, β-catenin, Vimentin, MMP2, MMP9, Snail and Slug in human colon cancer cells." (PMID 31905343, 2020). "Silencing HOTAIR elevates E-cadherin expression and suppresses that of vimentin and MMP-9, which can lead to EMT in colon cancer cells." (PMID 33246471, 2020). "Among the identified proteins within this category, vimentin (VIME, three protein species) and chloride intracellular channel 1 (CLIC1) were significantly up-regulated in colon cancer tissues." (PMID 32353950, 2020). "Vimentin and N-cadherin were chosen as mesenchymal-like markers, and CK20 was selected as colon cancer-specific epithelial marker." (PMID 31344798, 2019). "Upon treatment with IL-6, the 2 colon cancer cell lines showed decreased levels of E-cadherin and increased levels of phosphorylated STAT3, N-cadherin, SNAI1, and vimentin." (PMID 30308035, 2018). "E-cadherin downregulation and N-cadherin, vimentin, and α-smooth actin (α-SMA) upregulation together indicated that phthalate-treated colon cancer cells underwent EMT." (PMID 29568348, 2018). "This is notable since CDH1 and vimentin are involved in the EMT and cell motility control in human colon carcinoma." (PMID 28535802, 2017). "miR-223 upregulation in a colon cancer cell line upregulated c-Myc, cyclinD1, MMP7, and vimentin expression, downregulated E-cadherin, increased nuclear expression of β-catenin, and enhanced RhoA activation." (PMID 28969027, 2017). "Alcohol promotes expression of matrix metalloproteinases (MMP-2, -7, -9), and vimentin, and also phosphorylation and nuclear translocation of Snail involved in EMT by increasing epidermal growth factor receptor transactivation in colon cancer cells." (PMID 28538665, 2017). "We confirmed that relative to those with LGR5+ and KRASmut status, LGR5−/KRASwt colon carcinomas had decreased CDH1 and increased VIM and SLUG expressions, which are the expected changes in EMT biomarkers." (PMID 26744320, 2016). "Previous studies in colon carcinoma and multiple myeloma models showed that tumors with BCL9 KD exhibited altered expression and distribution of mesenchymal and epithelial markers, vimentin, β-catenin and E-cadherin, indicative of reduced EMT." (PMID 26384318, 2015). "Also, high CD44 expression is known to be positively correlated with vimentin levels and EMT features in various cancers, including gastric and colon cancers." (PMID 40518514, 2025). "Additional functional experiments and expression analyses of other key EMT markers, such as E-cadherin and Vimentin, as well as nuclear localization of Snail1, are needed to detail the net influence of the shell extract on EMT dynamics in these colon cancer cells." (PMID 41516111, 2025). "Our study with mouse colon cancer cell lines also clearly showed that overexpression of SOX2 led to increased expression of mesenchymal markers (vimentin and N-cadherin) and EMT-inducing transcription factors (e.g., TWIST1), supporting its role in promoting EMT in colon cancer." (PMID 40179020, 2025). "Whereas overexpression of CDK5RAP2 S down-regulated E-cadherin and up-regulated N-cadherin, Vimentin, Zeb1, Slug and Twist1 expression, indicating that CDK5RAP2 L and CDK5RAP2 S might have different roles in EMT of colon cancer cells." (PMID 39048555, 2024).
colon carcinoma (continued). "Conversely, when OLFM2 is knocked down in cells SW480 and SW620, there is an increase in E-cadherin expression and a decrease in N-cadherin and Vimentin expression.These findings indicate that OLFM2 plays an important role in promoting EMT in colon cancer cells." (PMID 38350902, 2024). "BGN and THBS2 knockdown significantly reduced colon cancer cells migration and invasion, as well as down‐regulating three EMT‐related proteins (Snail, Vimentin and N‐cadherin), and increasing the proliferation inhibitory effect of 5‐fluorouracil, irinotecan and oxaliplatin treatment." (PMID 36377223, 2022). "Another explanation is that the group of determinant CTCs had not been precisely identified, exemplified by the fact that only vimentin-positive CTCs were related to patients’ outcomes rather than EpCAM-positive CTCs in colon cancers." (PMID 35646680, 2022). "While the authors did not report an upregulation of vimentin in colon cancer cells growing as xenografts in mice but in the stroma, we observed the epithelial induction of vimentin in TROP2-positive cells even at early stages of colon tumorigenesis." (PMID 36077674, 2022). "It was observed that TGFβ stimulation increased the levels of MnSOD, fibronectin, vimentin, MMP-9, and N-cadherin and decreased the levels of occludin and E-cadherin in colon cancer cells above the basal level, indicating the mesenchymal-phenotype of these cells is promoted by TGFβ." (PMID 35883447, 2022). "It was shown that ADAM8 reduced the expression of epithelial markers (E‐cadherin) and increased the expression of mesenchymal markers (Vimentin and N‐cadherin), which indicated that ADAM8 could induce EMT in colon cancer cells." (PMID 32954649, 2020). "LncRNA HULC knockdown leads to a decrease in the expression of N-cadherin and vimentin, and an increased E-cadherin expression, indicating that HULC may be involved in the EMT process in colon cancer cells." (PMID 33246471, 2020). "Moreover, the expression of active caspase‐3, p21 and E‐cadherin was up‐regulated and the expression of cyclin D1, c‐Myc, vimentin, N‐cadherin and MMP9 was down‐regulated in OCA‐treated colon cancer cells." (PMID 33164339, 2020). "Therefore, immunohistochemical analysis was used to detect the expression of vimentin, Ki-67, and CD34 in colon cancer xenografts." (PMID 28358024, 2017). "For example, comparative analyses of LT97 microadenoma cells and SW620 colon carcinoma cells revealed that although vimentin is not detectable in LT97 cells, it is highly expressed in SW620 cells." (PMID 27072512, 2016). "Moreover, markers that induce or indicate EMT in colon cancer were significantly overexpressed in tumors with high CYB5R1 levels, including ZEB1 (r=0.20, p<0.0001), TWIST1 (r=0.22, p<0.0001), and VIM (r=0.29, p<0.0001)." (PMID 27120783, 2016). "In this study, we found that after colon cancer cells were treated with NCTD for 24 h, the protein level of p-ERK decreased, accompanied by an increase in the epithelial marker E-cadherin and a decrease in the mesenchymal markers N-cadherin and vimentin." (PMID 26846153, 2016). "Furthermore, SOX9 regulates E-cadherin, N-cadherin, vimentin and Snail expressions at protein and mRNA levels, mediates EMT, promotes colon cancer metastasis." (PMID 26755651, 2016). "In multivariate analysis of stage II–III human colon cancer patients, high expression of α-smooth muscle actin and vimentin but not stromal collagen, led to increase disease recurrence and decrease overall survival." (PMID 26104296, 2015). "It detected no signal in Dbait32Hc-transfected MCF-7 breast adenocarcinoma cells, which express keratin IFs, but not vimentin IFs as well as HCT116 colon cancer cell line lacking vimentin." (PMID 24282534, 2013). "In regard to chemosensitivity, vimentin expression was higher in colon carcinoma cell clones resistant to doxorubicin, although vimentin alone did not confer resistance." (PMID 17325702, 2007).
colon carcinoma (continued). "Although colon cancer cells did not express vimentin, we found that stromal vimentin expression was quite abundant." (PMID 17325702, 2007). "Western blotting revealed that the expression of the biomarkers of EMT, N-Cadherin, Vimentin, and Snail was downregulated or upregulated after SLC5A1 knockdown or overexpression, which further demonstrated that SLC5A1 could regulate colon cancer cell migration and invasion." (PMID 39781340, 2025). "Treatment of colon cancer xenografts with prolyl hydroxylase 2 (PHD2) could inhibit metastasis through the inhibition of the NF-κB signaling pathway and the downregulation of EMT-related proteins including vimentin." (PMID 36765706, 2023). "This may be because the group of determinant CTCs has not been precisely identified, as exemplified by the fact that only vimentin-positive CTCs were related to patient outcomes rather than EpCAM-positive CTCs in colon cancers." (PMID 35646680, 2022). "Moreover, our study demonstrated that knockdown of FXR in colon cancer cells induced EMT, accompanied by upregulation of Snail, Slug, vimentin, fibronectin, and MMP-9, and downregulation of E-cadherin and ZO-1, whereas ectopic expression of FXR had reversed change." (PMID 32807788, 2020). "Furthermore, AC also down-regulates the EMT-related gene such as vimentin and MMP3 with the upregulation of miRNA expression of miR142-3p across all the three colon cancer cells, implicating the key regulatory function of miR142-3p in colon cancer stemness and metastasis." (PMID 31349708, 2019). "Additionally, JSD could lead to an increase in expression of E-cadherin, and a decrease in expression of N-cadherin, Vimentin, p-AKT1, AKT1, p- GSK-3β, Snail, Slug, and Twist in colon cancer cells." (PMID 31772677, 2019). "In summary, JSD may downregulate the EMT transcription factors Snail, Slug and Twist through the AKT/GSK-3β signaling pathway, leading to an upregulation of E-cad, and downregulation of N-cad and Vimentin, reversing EMT and inhibiting invasion and metastasis of colon cancer cells." (PMID 31772677, 2019). "Therefore, we expect that CLSE may have anti-metastatic effects via regulation of E-cadherin, vimentin, MMP-2, and MMP-9 in colon cancer cells, and plan to undertake these experiments in the future." (PMID 29110726, 2017). "In addition, we have also measured the effect of CHST15 siRNA on the expression of EMT markers such as E-cadherin, vimentin, BMP7 and Wnt3 using TGF-β-stimulated colon cancer cell line and identified a significant suppression of these markers in the CHST15 siRNA treated cells." (PMID 27410685, 2016). "However, in colon cancer cell lines, we did not observe any change in the morphology, nor in E-cadherin or Vimentin protein levels upon Fra-1 depletion." (PMID 26646695, 2015). "In the pathogenesis of metastatic CRC, abundant miR-200c could be detected in liver metastasis tissues, and overexpression of miR-200c in colon cancer cell lines led to a reduced expression of its target genes ZEB1, ETS1 and FLT1, and EMT markers (E-cadherin and vimentin)." (PMID 26064956, 2015). "The immunofluorescence double staining in colon cancer cells (UICCIII/IV) with PDGF in combination with Cytokeratin illustrated a clear PDGF expression in epithelial colon cancer cells while PDGF expression in the stromal region (Vimentin staining) was considerably lower or absent." (PMID 27626684, 2016). "We investigated the role of vimentin, by carrying out the same assay with HCT116 colon cancer cells, which do not express vimentin but are, nevertheless, invasive and able to migrate." (PMID 24282534, 2013). "In this case, the poorly differentiated carcinomatous component was positive for epithelial and colon cancer markers (CK7, CK20, EMA, CDX2, and AFP) and the spindle-shaped pleomorphic sarcomatous component was strongly positive for vimentin, but negative for epithelial markers." (PMID 33765265, 2021).